TRAV14DV4 (T cell receptor alpha variable 14/delta variable 4)
Description:
V region of the variable domain of T cell receptor (TR) alpha chain that participates in the antigen recognition. Alpha-beta T cell receptors are antigen specific receptors which are essential to the immune response and are present on the cell surface of T lymphocytes. Recognize peptide-major histocompatibility (MH) (pMH) complexes that are displayed by antigen presenting cells (APC), a prerequisite for efficient T cell adaptive immunity against pathogens. Binding of alpha-beta TR to pMH complex initiates TR-CD3 clustering on the cell surface and intracellular activation of LCK that phosphorylates the ITAM motifs of CD3G, CD3D, CD3E and CD247 enabling the recruitment of ZAP70. In turn ZAP70 phosphorylates LAT, which recruits numerous signaling molecules to form the LAT signalosome. The LAT signalosome propagates signal branching to three major signaling pathways, the calcium, the mitogen-activated protein kinase (MAPK) kinase and the nuclear factor NF-kappa-B (NF-kB) pathways, leading to the mobilization of transcription factors that are critical for gene expression and essential for T cell growth and differentiation. The T cell repertoire is generated in the thymus, by V-(D)-J rearrangement. This repertoire is then shaped by intrathymic selection events to generate a peripheral T cell pool of self-MH restricted, non-autoaggressive T cells. Post-thymic interaction of alpha-beta TR with the pMH complexes shapes TR structural and functional avidity.
Synonyms: TRAV14/DV4; TCRAV6S1-hDV104S1; hADV14S1
Gene: T-cell receptor variable (V) gene on chromosome 14 (21,924,063 to 21,924,651, forward strand). Ensembl gene ENSG00000211792.
Subcellular location: Cell membrane
Gene Ontology:
Biological process: immune response
Cellular component: immunoglobulin complex; plasma membrane
Homologues: Paralogues in human: TRAV19 (56% identical), TRDV1 (55% identical), TRDV3 (30% identical), TRAV18 (28% identical), IGLV11-55 (27% identical), IGKV3-15 (26% identical), IGKV3D-15 (26% identical), IGKV3-7 (25% identical), IGKV3OR2-268 (25% identical), IGLV2-18 (25% identical), IGLV5-37 (25% identical), IGLV5-52 (25% identical), and 81 more.